SNORA25 (small nucleolar RNA, H/ACA box 25)
Synonyms: ACA25; SNORA25A
Gene: Small nucleolar RNA gene on chromosome 11 (93,730,513 to 93,730,646, reverse strand). Ensembl gene ENSG00000207112.
Gene Ontology:
Biological process: RNA processing
Cellular component: nucleolus
Homologues: Orthologues: chimpanzee SNORA25 (99% identical), macaque SNORA25 (96% identical). Paralogues in human: SNORA25B (83% identical).